CCNL1 (cyclin L1)
Description:
Regulatory component of the cyclin-L-CDK11 complex that regulates transcription and pre-mRNA splicing. Inhibited by the CDK-specific inhibitor CDKN1A/p21. May be a candidate proto-oncogene in head and neck squamous cell carcinomas (HNSCC).
Synonyms: BM-001; ania-6a; ANIA6A; PRO1073
Tractability: PROTAC: UniProt records ubiquitination sites on it; ubiquitination databases record sites on it; its protein half-life has been measured.
Gene: Protein-coding gene on chromosome 3 (157,146,508 to 157,160,760, reverse strand). Ensembl gene ENSG00000163660.
Subcellular location: Nucleus speckle; Nucleus, nucleoplasm
Subcellular location (Human Protein Atlas): Nuclear bodies; Nucleoplasm
Gene Ontology:
Molecular function: cyclin-dependent protein serine/threonine kinase regulator activity; protein binding
Biological process: regulation of mRNA splicing, via spliceosome; regulation of RNA splicing; regulation of apoptotic process; regulation of cell cycle; regulation of centrosome cycle; regulation of transcription by RNA polymerase II
Cellular component: cyclin L-CDK11 complex; cyclin-dependent protein kinase holoenzyme complex; nuclear body; nuclear speck; nucleoplasm; nucleus
Genetic constraint (gnomAD): Loss-of-function variants: 13 observed, 54.34 expected, observed/expected ratio (o/e) 0.24, 90% interval 0.16 to 0.38. The upper end of that interval is the gene's LOEUF score, 0.38, which puts it in group 1 of 6, group 1 being the genes least tolerant of losing a copy. Missense variants: 460 observed, 652.94 expected, observed/expected ratio (o/e) 0.7, 90% interval 0.65 to 0.76. Synonymous variants: 263 observed, 242.89 expected, observed/expected ratio (o/e) 1.08, 90% interval 0.98 to 1.2.
Homologues: Orthologues: chimpanzee CCNL1 (100% identical), macaque CCNL1 (100% identical), pig CCNL1 (99% identical), rat Ccnl1 (98% identical), mouse Ccnl1 (98% identical), dog CCNL1 (98% identical), rabbit CCNL1 (85% identical), tropical clawed frog ccnl1 (79% identical), zebrafish ccnl1a (78% identical), Caenorhabditis elegans cit-1.2 (19% identical), Drosophila melanogaster CycT (18% identical), Caenorhabditis elegans cit-1.1 (14% identical), and 2 more. Paralogues in human: CCNL2 (60% identical), CCNT2 (25% identical), CCNT1 (22% identical), CCNK (20% identical), CCNQ (14% identical), CCNH (10% identical).